NNMT (nicotinamide N-methyltransferase)
Diseases named in the same sentence as NNMT in open-access papers (continued):
Sharing a sentence is not in itself a finding about the gene and the disease.
metabolic disorders (15 papers, 2016 to 2024). "The dysregulation of NNMT expression is closely associated with the risk of metabolic diseases such as obesity and diabetes." (PMID 38838088, 2024). "Targeted inhibition of NNMT improves the energy metabolism of skeletal muscles and alleviates muscle damage caused by metabolic disorders through regulating the NAD+/AMPK axis in both the D‐galactose‐treated mouse model and the naturally aging mouse model." (PMID 38838088, 2024). "NNMT regulates energy metabolism and may also exert a causal role in metabolic disorders." (PMID 32000734, 2020). "Various inhibitors have been developed for the research and exploration of metabolic diseases based on the physiological functions and main regulatory pathways of NNMT." (PMID 38838088, 2024). "Overexpression of NNMT and the presence of the active metabolite MNA is associated with a number of diseases including metabolic disorders." (PMID 36104373, 2022). "Studies have shown that inhibiting NNMT can protect the liver from lipotoxicity, further elucidating its potential clinical application in metabolic diseases." (PMID 36225559, 2022). "Several NNMT inhibitors, which are expected to be useful for the treatment of metabolic disorders, have been developed and are available commercially." (PMID 34655178, 2021). "Our findings demonstrate the possibility that NNMT inhibitors, which are expected to be used for the treatment of metabolic disorders, would be effective for the treatment of aggressive EC." (PMID 34655178, 2021). "On-going efforts are focused on further establishing the potential of such NNMT inhibitor prodrugs in a range of cellular and in vivo assays relevant to both oncology and metabolic disease." (PMID 34572571, 2021). "Therefore, NNMT has been demonstrated as a promising target for the treatment of some metabolic diseases and tumors." (PMID 38838088, 2024). "However, till date there are no reports on the feasibility of using small molecule modulators of NNMT in preclinical animal models of metabolic disease to validate NNMT as a pharmacological drug target." (PMID 29483571, 2018). "In animal models of metabolic diseases, JBSNF-000028 and JBSNF-000088 were identified to inhibit human and mouse NNMT activity." (PMID 38919254, 2024). "Here we report a small molecule analog of NA, JBSNF-000088, that inhibits NNMT activity, reduces MNA levels and drives insulin sensitization, glucose modulation and body weight reduction in animal models of metabolic disease." (PMID 29483571, 2018).
cardiovascular disease (7 papers, 2016 to 2025). "Our previous works indicate that NNMT is involved in the body mass index and energy metabolism, and recently the association between a SNP (rs694539) of NNMT and a variety of cardiovascular diseases was reported." (PMID 27999813, 2016). "Our previous studies also found genetic associations between NNMT gene and cardiovascular diseases." (PMID 38921477, 2024). "Since the expression of NNMT is directly determined by NNMT, the roles of NNMT in the development of cardiovascular diseases have been reported in recent years." (PMID 27999813, 2016). "Interestingly, NNMT expression has been found to be positively associated with LDL levels and negatively associated with HDL levels, both of which are factors associated with cardiovascular disease." (PMID 38921477, 2024). "Notably, NNMT expression has been found to be positively correlated with LDL levels and negatively correlated with HDL levels, both of which are relevant factors in cardiovascular diseases." (PMID 38919254, 2024).
Gastrointestinal Neoplasms (2 papers, 2022 to 2023). "We note that NNMT is an important enzyme that regulates metabolism, and that ERS-induced upregulation of NNMT promotes the development of alcohol-related fatty liver." (PMID 37107704, 2023).
infection (2 papers, 2023 to 2025). The state of being infected such as from the introduction of a foreign agent such as serum, vaccine, antigenic substance or organism. "NAMPT and NNMT mRNA were upregulated compared to untreated controls after both Spn D39 infection and stimulation with the bacterial cell wall component lipoteichoic acid (LTA) for 9 or 16 h." (PMID 37783679, 2023). "Our multi-omics approach revealed that in response to Spn D39 infection, NAMPT and NNMT are upregulated in bronchial epithelial BEAS-2B cells as part of a general, pro-inflammatory response." (PMID 37783679, 2023).
neurodegenerative disease (2 papers, 2018 to 2023). A disorder of the central nervous system characterized by gradual and progressive loss of neural tissue and neurologic function. "To date, this is the only report of a critical defect in NNMT activity manifesting in adulthood and leading to neurodegenerative disease." (PMID 36984839, 2023).
neurological disorders (1 paper, 2018). "In summary, ANMT-1/NNMT is a pivotal element in neuronal cell metabolism that regulates neuronal homeostasis and may contribute to the prevalence of neurological disorders." (PMID 30192747, 2018).
NNMT also shares sentences with these, for which no sentence is quoted: fatty liver (7 papers); esophageal squamous cell carcinoma (6); nasopharyngeal carcinoma (3); steatosis (3); stomach adenocarcinoma (3); chronic kidney disease (2); Cirrhosis (2); Hepatic fibrosis (2); lung squamous cell carcinoma (2); Merkel cell carcinoma (2); non-alcoholic fatty liver disease (2); pancreatic adenocarcinoma (2); sarcoma (2); squamous cell carcinoma (2); stomach cancer (2); adrenocortical carcinoma (1); alcoholic fatty liver disease (1); breast invasive carcinoma (1); cholangiocarcinoma (1); chronic pancreatitis (1); colitis (1); colorectal adenoma (1); colorectal tumor (1); coronary artery disease (1); dementia (1); endometrial tumor (1); epithelial neoplasm (1); fibrosis (1); glomerulonephritis (1); glomerulosclerosis (1).
A further 22 diseases each share a sentence with NNMT in 1 paper.